KCNV1 (potassium voltage-gated channel modifier subfamily V member 1)
Description:
Potassium channel subunit that does not form functional channels by itself.
Synonyms: Kv8.1; HNKA; KCNB3; KV2.3
Tractability: Small molecule: an approved drug acts on it; it belongs to a druggable protein family. Antibody: UniProt places it where antibodies can reach, with high confidence; its Gene Ontology location is reachable by antibodies, with high confidence; UniProt predicts a signal peptide or a membrane-spanning region; the Human Protein Atlas places it where antibodies can reach.
Gene: Protein-coding gene on chromosome 8 (109,963,636 to 109,975,771, reverse strand). Ensembl gene ENSG00000164794.
Subcellular location: Cell membrane
Subcellular location (Human Protein Atlas): Cytokinetic bridge; Plasma membrane
Pathways (Reactome):
Neuronal System: Voltage gated Potassium channels
Gene Ontology:
Molecular function: protein binding; ion channel inhibitor activity; potassium channel regulator activity; monoatomic ion channel activity; voltage-gated potassium channel activity
Biological process: action potential; potassium ion transmembrane transport; potassium ion transport; monoatomic ion transport; protein homooligomerization; transmembrane transport
Cellular component: plasma membrane; membrane; voltage-gated potassium channel complex
Genetic constraint (gnomAD): Loss-of-function variants: 2 observed, 35.6 expected, observed/expected ratio (o/e) 0.0562, 90% interval 0.022 to 0.18. The upper end of that interval is the gene's LOEUF score, 0.18, which puts it in group 1 of 6, group 1 being the genes least tolerant of losing a copy. Missense variants: 321 observed, 635.68 expected, observed/expected ratio (o/e) 0.5, 90% interval 0.46 to 0.55. Synonymous variants: 280 observed, 260.57 expected, observed/expected ratio (o/e) 1.07, 90% interval 0.97 to 1.19.
Homologues: Orthologues: macaque KCNV1 (100% identical), chimpanzee KCNV1 (99% identical), pig KCNV1 (98% identical), rabbit KCNV1 (97% identical), guinea pig KCNV1 (97% identical), mouse Kcnv1 (96% identical), rat Kcnv1 (95% identical), tropical clawed frog kcnv1 (67% identical), zebrafish kcnv1 (64% identical). Paralogues in human: KCNB2 (42% identical), KCNS3 (38% identical), KCNS2 (37% identical), KCNS1 (34% identical), KCNV2 (32% identical), KCNF1 (31% identical), KCNG1 (31% identical), KCND1 (30% identical), KCNG4 (30% identical), KCND2 (29% identical), KCNG2 (29% identical), and 19 more.
Diseases named in the same sentence as KCNV1 in open-access papers:
KCNV1 is named in the same sentence as 16 diseases in open-access papers, as found by Europe PMC text mining. Sharing a sentence is not in itself a finding about the gene and the disease. The quoted sentences say what the papers report.
amyotrophic lateral sclerosis (1 paper, 2024). Amyotrophic lateral sclerosis (ALS) is a neurodegenerative disease characterized by progressive muscular paralysis reflecting degeneration of motor neurons in the primary motor cortex, corticospinal tracts, brainstem and spinal cord. "To test if this observation also holds for other amyotrophic lateral sclerosis mutations, we examined KCNV1 expression in MNs differentiated from iPSCs harbouring C9orf72 hexanucleotide repeat expansions." (PMID 38911266, 2024). "Amyotrophic lateral sclerosis is characterized by a progressive loss of MNs, and we wondered whether KCNV1 may impact neuronal survival." (PMID 38911266, 2024). "How does a reduction of KCNV1/Kv8.1 contribute to amyotrophic lateral sclerosis–related MN cell death?" (PMID 38911266, 2024). "We also found that KCNV1 interacts with Kv2.2 that may contribute to amyotrophic lateral sclerosis pathogenesis." (PMID 38911266, 2024).
bladder cancer (1 paper, 2023). "A 5-gene panel (VAX1, CFTR, KCNV1, PROX1, and TAL1) had an 88.7% sensitivity and an 87.3% specificity for the diagnosis of bladder cancer." (PMID 37627900, 2023). "The methylation frequency of eight genes (VAX1, ECEL1, KCNV1, LMX1A, PROX1, SLC6A20, TAL1, and TMEM26) was significantly higher in the urine of bladder cancer patients as compared to that of normal controls." (PMID 37627900, 2023).
breast carcinoma (1 paper, 2020). "Methyl-DNA binding domain capture technique identified Kcnv1 as a diagnostic marker for early noninvasive detection and subsequent breast cancer surveillance." (PMID 32190687, 2020). "This suggested that lncRNA interacted with Kcnv1 modification methylation levels to mediate survival in TN breast cancer." (PMID 32190687, 2020).
preeclampsia (1 paper, 2020). Preeclampsia is a hypertensive disorder of pregnancy that is characterized by new-onset hypertension with proteinuria presenting after 20 weeks of gestation, and depending on mild or severe forms may initially present with severe headache, visual disturbances, and hyperreflexia. "Meanwhile, the Kcnv1, voltage-gated channels have been reported as one of the gene expressed in preeclampsia, a hypertensive condition in pregnant women." (PMID 32175184, 2020).
sporadic amyotrophic lateral sclerosis (1 paper, 2024). Sporadic amyotrophic lateral sclerosis is a amyotrophic lateral sclerosis in which there is no known cause, such as no family history. "While the expression of Kv8.1 and Kv2.2 have not been reported to be altered in SOD(A4V) transgenic mice, KCNV1/Kv8.1 is reduced in the motor cortex of sporadic amyotrophic lateral sclerosis patients." (PMID 38911266, 2024).
cancer (2 papers, 2012 to 2021). A tumor composed of atypical neoplastic, often pleomorphic cells that invade other tissues. "The remaining other 4 genes, VAX1 KCNV1, ECEL1 and TMEM26, were found in the present study to be hypermethylated in BC, but there were no any background record that provided mechanisms in the carcinogenesis and development of any cancer, let alone BC." (PMID 22529986, 2012).
tumor (1 paper, 2024). "Additionally, voltage-gated ion channels and genes like KCNQ5, KCNV1, ADAMTS14, MPPED1, and SLC24A2 are linked to tumor traits in these tumors." (PMID 39139281, 2024).
KCNV1 also shares sentences with these, for which no sentence is quoted: Cognitive impairment (1 paper); developmental delay and (1); Dravet syndrome (1); epilepsy (1); Intellectual disability (1); rheumatoid arthritis (1); Temple-Baraitser syndrome (1); Timothy syndrome (1); type 1 diabetes mellitus (1).